CFH (complement factor H)
Diseases named in the same sentence as CFH in open-access papers (continued):
Sharing a sentence is not in itself a finding about the gene and the disease.
viral hepatitis (1 paper, 2016). An acute or chronic inflammation of the liver parenchyma caused by viruses. "CFH functions as a cofactor in the inactivation of C3b by factor I, which can interact with IgG and is moderately depressed in the serum of patients with viral hepatitis." (PMID 28025641, 2016).
tumor (55 papers, 2002 to 2026). "CFH can promote tumor-associated macrophages (TAMs) polarization towards an immunosuppressive M2-like phenotype, characterized by the release of immunosuppressive and anti-inflammatory cytokines." (PMID 38389705, 2024). "After demonstrating that CFH is the target of GT103 in EVs, we surveyed several tumor cell lines and found that CFH was more prevalent in the EVs of the metastatic variants of B16 and LLC than the parental cell lines." (PMID 34133431, 2021). "A CFH‐deficient mouse model revealed an elevation in inflammatory signalling pathways and an increase in spontaneous tumour formation in the liver." (PMID 33708358, 2020). "The remaining investigated assays detect the human complement factor H and related protein (the Bladder Tumour-associated Antigen) which is reported to be a marker for BC." (PMID 22162681, 2011). "However, dysregulation of CFH expression and function in the context of cancer has also been linked to immune evasion, fostering tumor development and metastasis." (PMID 38389705, 2024). "In addition, high levels of CFH in the tumor cell membrane are associated with a poor prognosis." (PMID 39747856, 2025). "Recent studies have confirmed that tumor cells can “hijack” the complement system by overexpressing CFH, thereby evading complement attack." (PMID 41163355, 2025). "This suggests that the antibody binding to the tumor cell-expressed CFH is required for its activity." (PMID 39747856, 2025). "Despite growing evidence for the role of CFH in tumor immunity, its clinical utility as a systemic biomarker remains unexplored." (PMID 40647461, 2025). "It has been shown that tumor cells have binding sites for both complement factor H and AM, and that the presence of these molecules effectively blocks complement-mediated cytotoxicity." (PMID 40539045, 2025). "This study investigated serum CFH as a candidate biomarker for tumor aggressiveness and treatment outcomes in cSCC." (PMID 40647461, 2025). "CD55 and CFH were explored as predefined candidate IHC biomarkers and using archival tumor specimens from the time of initial diagnosis." (PMID 39747856, 2025). "GT103 is a first-in-class, fully human, IgG3 monoclonal antibody targeting complement factor H that kills tumor cells and promotes anti-cancer immunity in preclinical models." (PMID 39747856, 2025). "CFH-mediated immunosuppression enhances tumor cells’ ability to avoid immune recognition and produce an immunosuppressive tumor microenvironment." (PMID 38389705, 2024). "These mAbs can potentially block CFH’s interactions with complement components, permit complement activation of tumor cells, while driving anti-tumor immune program." (PMID 38389705, 2024). "Increased CFH expression has also been detected in tumor tissues relative to neighboring normal tissues in this disease." (PMID 38389705, 2024). "As a therapeutic strategy to boost anti-tumor immune responses and better patient outcomes, targeting CFH shows promise." (PMID 38389705, 2024). "Further, by modulating the complement cascade, CFH can limit the production of pro-inflammatory complement fragments C3a and C5a and suppress immune cell-mediated tumor destruction." (PMID 38389705, 2024). "The following five mechanisms have been proposed to explain how CFH helps cancer cells to evade complement-mediated toxicity or immune responses and advance tumor growth." (PMID 38389705, 2024). "These immunotherapeutic approaches have the potential to increase immune surveillance and promote anti-tumor immune responses and need to be explored as anti-CFH therapy for cancer." (PMID 38389705, 2024). "CFH peptides or fusion proteins can be used as antigens in these vaccines to elicit specific immune responses against CFH-expressing tumor cells." (PMID 38389705, 2024). "Further, chemotherapeutic drugs can be used in conjunction with CFH-targeted therapies to take advantage of the immunomodulatory effects of CFH inhibition while also specifically targeting tumor cells." (PMID 38389705, 2024).
tumor (continued). "As a transcription factor associated with development of regulatory T cells and, due to our results showing elevated CFH in these tumor samples, we expected FOXP3 staining to be more intense within the immune infiltrate surrounding tumor tissue (arrows)." (PMID 35223500, 2022). "It is possible that in the early stages of an immune response to developing tumors, IFN-γ secretion leads to increased CFH expression which ultimately derails the immune response and allows tumor progression." (PMID 35223500, 2022). "We verified that CFH is produced by cells cultured from these tumor and adjacent normal tissue samples using immunofluorescent staining for CFH." (PMID 35223500, 2022). "GT103 acts through CFH to kill tumor cells by promoting complement activation, culminating in the formation of the lytic MAC." (PMID 34133431, 2021). "It was recently shown that CFH-enriched HCC-derived exosomes promote HCC cell growth, migration and liver metastasis formation and these effects are negated by a tumor-specific antibody to CFH." (PMID 34133431, 2021). "Lastly, we demonstrated the therapeutic efficacy of an anti‐CFH antibody in suppressing tumour formation in a syngeneic mouse model." (PMID 33708358, 2020). "Anti‐CFH antibodies purified from these NSCLC patients recognize a conformationally distinct form of CFH, when bound to the tumour cell surface." (PMID 33708358, 2020). "In contrast to promoting tumor progression, components such as C2 and CFH exhibit tumor-suppressive effects and better prognosis in HCC patients." (PMID 33718121, 2020). "This study suggests a new therapeutic strategy for HCC, by inhibiting EV‐CFH with a tumour specific anti‐CFH antibody." (PMID 33708358, 2020). "In this study, we revealed that blocking CFH‐enriched EVs using anti‐CFH antibody delayed tumour development and metastasis." (PMID 33708358, 2020). "Collectively, these data point towards treatment options that enhance CFH/CFHR levels either by gene therapies or by CFH reconstitution to lower tumor burden in HCC." (PMID 33718121, 2020). "Blocking EV-CFH with a tumor specific anti-CFH antibody showed reduction in liver tumor promoting potentials and a potential therapeutic target." (PMID 33718121, 2020). "The tumor-suppressive effects of CFH in liver carcinogenesis were further confirmed by analyzing gene expression and methylation profiles in patients with HCC." (PMID 33718121, 2020). "Expression of the two main soluble inhibitors of the complement system, CFI and CFH, have been detected in cSCC tumor cells in culture and in vivo and the expression correlates with the progression of cSCC and the expression in normal skin is negative or weak." (PMID 31331124, 2019). "For instance, CFH has been known to inhibit the complement pathway and to contribute to tumor growth." (PMID 30828525, 2019). "From the six signature proteins (HLA-A, CFH, CD44, PTPRJ, HP, and CDH5), only CD44 has been previously associated with CRC prognosis in tumor specimens from 74 patients that were assayed by immunohistochemistry." (PMID 26253080, 2015). "These anti-CFH autoantibodies were found to recognize a conformationally unique CFH epitope hypothesized to be presented on the surface of tumor cells." (PMID 38389705, 2024). "Additionally, the 14-3-3ζ protein in EVs impairs tumor-infiltrating T lymphocyte functions, while complement factor H (CFH) and circular RNAs (circRNAs) regulate immune evasion and cell signaling." (PMID 37896221, 2023). "In addition to C3 and CFH, cancer cells have been shown to produce and secrete other complement proteins that suppress anti-tumor immunity." (PMID 35860237, 2022). "In addition, CFH has recently been shown to have intracellular activities and to promote tumor progression independently of the canonical extracellular role of complement." (PMID 35223500, 2022).
tumor (continued). "Recent studies show that enhanced CFH or CFHR (CFHR1 and CFHR3) levels either by gene therapies or by CFH reconstitution might lower tumor burden in HCC." (PMID 34813686, 2022). "A xenograft tumor model was established to uncover the function of circ-CFH in vivo." (PMID 35415236, 2022). "In a syngeneic mouse model, anti‐CFH antibody significantly suppressed tumour development." (PMID 33708358, 2020). "Furthermore, complement C3, C3a, C4, C4a, and C7 have been identified as biomarkers in HCC diagnosis while C7 and CFH are recognized for their critical roles in mediating stemness of tumor-initiating cells." (PMID 33718121, 2020). "Additionally, it was reported that tumor cells expressing CFH on their surface can prevent C3b accumulation on their cell membranes and increase the resistance of these cells to complement-mediated lysis." (PMID 30987235, 2019). "Complement factor H (CFH) is implied to play a role in tumor growth and metastasis." (PMID 31130605, 2019). "CFH may help tumor cells evade immune surveillance, promoting metastasis." (PMID 40276062, 2025). "In addition to using monoclonal antibodies to target CFH, small molecule inhibitors that can disrupt CFH’s interaction with tumor cells and immune cells can be created as therapeutic agents and utilized as single agents or in combination with other therapies to improve their efficacy." (PMID 38389705, 2024). "Furthermore, gene editing techniques, such as CRISPR-Cas9, can be used to alter CFH expression in tumor cells and could potentially be used as anti-cancer therapy." (PMID 38389705, 2024). "Complement factor H (CFH) and Complement factor I (CFI) modulated the fundamental processes of the tumor cell, promoting proliferation and tumor progression when tested in animal models." (PMID 39865094, 2025). "Bioinformatics analysis revealed that APOC1, CFH, LGALS1 and NUSAP1 were highly expressed in bone metastases compared to primary tumours, whereas ADRB2, NR4A2 and ZNF331 exhibited the opposite trend (p < 0.05)." (PMID 39098992, 2024). "Targeting CFH and its related molecular pathways is a novel therapeutic approach to modify the TME, improve anticancer immune responses, and decrease tumor growth and spread." (PMID 38389705, 2024). "In the present research, circ-CFH was highly expressed in HCC tissues and cells, and its high expression was closely related to tumor metastasis and the TNM stage." (PMID 35415236, 2022). "EVs complement factor H (CFH) elevates C3a and C5a levels, exacerbating inflammatory responses and tumor growth." (PMID 35692794, 2022). "Thus, this work demonstrates CFH is expressed on tumor cell derived exosomes, can protect them from complement lysis and phagocytosis, and that an anti-CFH antibody can be used to target tumor-derived exosomes for exosome destruction via innate immune mechanisms." (PMID 34133431, 2021). "The autoantibody binds to a very specific functional domain of CFH in SCR 19, blocks binding of CFH to C3b on the tumour cell, and thus promotes complement‐dependent tumour cell lysis with subsequent inhibition of tumour growth." (PMID 33708358, 2020). "RT–PCR and immunohistochemistry on independent cases validated prognostic significance for several genes including RECQL4, FRRS1, CFH and MET – whose combined expression carried greater prognostic value than tumour grade – and cmet and TRKB proteins." (PMID 18382428, 2008). "It has been shown that tumor cell-expressed indoleamine 2,3-dioxygenase 1 increased CFH and FHL-1 expression independent of tryptophan metabolism resulting in Treg proliferation and activation." (PMID 38389705, 2024). "In renal cell carcinoma, intracellular CFH has been reported to drive tumor growth independent of the complement cascade." (PMID 38389705, 2024). "Besides, the silencing of circ-CFH inhibited RNF38 and circ-CFH expression while it enhanced miR-377-3p expression in xenograft tumor tissues." (PMID 35415236, 2022).
tumor (continued). "Given that increased CFH and CFI would decrease C3a and C5a levels, increased CFH would not favor tumor progression through canonical complement pathways." (PMID 35223500, 2022). "On the other hand, osteopontin (OPN), another downstream target of LSF-1, can inhibit the lytic activity of the alternative complement pathway by binding to CFH on the cell surface and therefore prevent tumour cells from immune surveillance, indicating the complex interaction between LSF-1 and CFH." (PMID 36341431, 2022). "OPN sequesters CFH on the surface of the tumor cells and hinders the formation of membrane attack complex (MAC), effectively preventing complement-mediated lysis and enabling tumor cells to escape immune surveillance." (PMID 33718121, 2020). "Moreover, knockdown of CFH and CFI in cSCC tumor cells results in significant inhibition of cell viability and migration in association with potent inhibition of ERK1/2 activation." (PMID 31331124, 2019). "They found that nonenzymatic tumor cell IDO1 activity increased expression of complement factor H (CFH) and its isoform, factor H like protein (FHL-1) in human GBM, resulting in increased intratumoral Tregs and myeloid-derived suppressor cells, accelerated tumor growth and poor survival." (PMID 37876966, 2023). "circ-CFH was overexpressed in HCC tissues and cells, and the downregulation of circ-CFH inhibited the development of HCC by repressing cell proliferation, migration, invasion, and glycolysis while enhancing apoptosis in vitro, as well as inhibited tumor growth in vivo." (PMID 35415236, 2022). "The MFP proteome was enriched for several immune-related and plasma proteins more indicative of inflammatory infiltration and chronic immune activation rather than tumor-specific remodeling including C1QB, CFH, MZB1, IGKV3-20, ORM2, ALB, and AZGP1." (PMID 41007761, 2025). "GT103 recognizes the same epitope as the anti-CFH autoantibody, induces CDC of tumor cells, and does not bind native, soluble CFH in blood." (PMID 34133431, 2021).
infection (37 papers, 2008 to 2025). The state of being infected such as from the introduction of a foreign agent such as serum, vaccine, antigenic substance or organism. "Specifically, 70% of cases of aHUS with mutations in CFH are preceded by an infection." (PMID 25373393, 2014). "Therefore, in terms of viral clearance, the reduced binding affinity of the Y402H variant could be associated with a decreased effectiveness of CFH in the downregulation of the C3bBb AP convertase and weaker opsonization dynamics during infection." (PMID 35877417, 2022). "In Edwardsiella tarda, it acts as an anti-complement factor and a cellular infection promoter by binding to complement factor H and inhibiting the alternative pathway of complement activation." (PMID 39809778, 2025). "These are involved in smooth-muscle function (FGFR1, GATA5 and STIM1), tissue organization (ADAMTS10), alveolar and epithelial function (ABCA3 and CLDN18), and inflammation and immune response to infection (CFH, CYTL1, HMCN1, LRBA and STIM1)." (PMID 36914875, 2023). "The alteration of proteins involved in blood coagulation was also found in 2 and 4 weeks after infection, namely complement factor H and protein AMBP." (PMID 35271623, 2022). "Two weeks after infection, 2 out of 5 mouse serum proteins were upregulated (mouse complement factor H [FH] and UDP-N-acetylhexosamine pyrophosphorylase)." (PMID 35271623, 2022). "In a previous study (data not published), our group detected a similar upregulation of CFH expression in gill tissue and serum of salmon which had experienced a single infection with P. perurans." (PMID 34062978, 2021). "In that case the upregulation of CFH was apparent in the context of a subdued immune response to infection." (PMID 34062978, 2021). "CFH (Complement Factor H) mediates a number of essential biological functions that participate in host defense against infection, initiation of the inflammatory reaction, processing, and clearance of immune complexes, and regulation of the immune response." (PMID 24558588, 2012). "In addition, the expression of c1ql2, C3, C5, C7, C9, CFB, and complement factor H (CFH) was regulated in rainbow trout stimulated with β-glucan upon infection with A. salmonicida, suggesting improved immune enhancement." (PMID 34835165, 2021). "A recent study described a relation between CFH and CFHR structural variants and infection, suggesting that dysfunctional CFH could not adequately control the complement activation induced by exposure to pathogens." (PMID 41333025, 2025). "Therefore, similarly to rs1061170, the reduced binding affinity of the rs1065489 (E936D) SNP could also contribute to the decreased contribution dynamics of CFH in the downregulation of the C3bBb AP convertase and the opsonization processes during infection." (PMID 35877417, 2022). "A complement effect on homeostasis during infection is determined by both cytotoxic (activate complement component 5 (C5a) terminal cytotoxic complex (TCC)), and cytoprotective elements (complement factor H (FH), as well as apolipoprotein E (ApoE))." (PMID 35953544, 2022). "Several regulators of the complement system, including complement factor H, complement factor I, and CD59, are downregulated by SARS-CoV-2, which may contribute to complement dysregulation during infection." (PMID 39040605, 2024). "Plasma proteins that were identified at the sites of infection included fibronectin, all isoforms of fibrinogen, and complement factor H, although notably some of these were absent in some samples." (PMID 29654237, 2018). "However, the corresponding upregulation of CFH, a complement regulator, suggests that an alternative pathway could also be activated, which in the absence of infection could indicate damaged tissue." (PMID 31703110, 2019).
infection (continued). "Furthermore, a broad activation pattern of the complement system—encompassing both effector components (e.g., C2, C3, C8A, C9) and regulatory proteins (e.g., CFH, CFI, C1QB)—is consistent with prolonged innate immune stimulation in the absence of active infection." (PMID 40869330, 2025).